IL22 (interleukin 22)
Diseases named in the same sentence as IL22 in open-access papers (continued):
Sharing a sentence is not in itself a finding about the gene and the disease.
tumor (continued). "At the early stage of cancer metastasis, IL-22 produced by tissue-resident iNKT17 cells facilitates the extravasation of cancer cells into the liver, and CD4+TRM cell-derived IL-22 promotes tumor metastasis at the late stage." (PMID 39820040, 2025). "ILC3s play a multifaceted role in cancer immunity, with anti-tumor effects primarily driven by their ability to recruit and activate effector cells, produce cytokines like IL-22 and TNF, form TLS, and present antigens." (PMID 40963622, 2025). "Recent research on the role of IL-22 in tumor angiogenesis offers deeper insights into how TH17 cells contribute to cancer development and progression." (PMID 40806452, 2025). "This tumour‐promoting function of IL‐22 through STAT3 activation has also been demonstrated in HCC and NSCLC." (PMID 40899118, 2025). "In our experiment, the maximum level of ILC3 frequency was coupled with up-regulation of the IL-22 gene, which was detected in the early stage of 4T1 tumor growth and the late stage of MC4-L2 tumor development." (PMID 39877637, 2025). "In preclinical models of tumorigenesis in the intestine, blocking IL-22 or its receptor suppresses tumor growth and enhances the response to immunotherapy." (PMID 40806452, 2025). "In terms of its mechanism of action, IL-26 stimulates IL-22-producing cells, which subsequently suppress cytotoxic T-cell function and facilitate tumor progression through activation of anti-apoptotic signaling pathways." (PMID 41515435, 2025). "In a model of bacterial‐driven colitis‐associated cancer, the production of IL‐22 is crucial for sustaining CRC, activating the STAT3 signalling pathway in epithelial cells, thereby enhancing proliferation and supporting tumour growth." (PMID 40899118, 2025). "Among the evaluated cytokines in the early stage of MC4-L2 tumors, only a rise in IL-10 expression was detected; after tumor progression, IL-13 and IL-22 were overexpressed in addition to IL-10." (PMID 39877637, 2025). "For example, IL-22 promotes tumor growth by enhancing cancer cell proliferation and protecting against apoptosis, whereas IL-24 demonstrates anti-tumor activity by inducing cancer cell death and inhibiting metastasis." (PMID 40806452, 2025). "Intra-tumor IL22-producing Th22 cells, which proportion is increased in tumor tissues, is associated with poor prognosis in several cancer types." (PMID 41310721, 2025). "We observed that IL-16, IL-17, IL-22, and IL-26 are specifically expressed in Tc17 cells, and their corresponding receptors are also highly expressed in tumor cells." (PMID 40452847, 2025). "APS-1 patients carry AIRE mutations that lead to autoantibodies against IL-17A/F, IL-22 and type I interferons (IFN-α/ω) and impair Th17 antifungal immunity and tumor surveillance." (PMID 41009535, 2025). "IL-23 stabilizes the Th17 phenotype and promotes expression of pro-tumor mediators such as IL-17A, IL-22, and GM-CSF, while inhibiting anti-tumor features such as IFN-γ production." (PMID 41181112, 2025). "Our data indicate that Tc17 cells highly express a range of cytokines, notably IL-16, IL-17A, IL-17F, IL-22, and IL-26, and it is these five cytokines for which receptors are also highly expressed in tumor cells." (PMID 40452847, 2025). "ILC3s are key producers of IL‐22, and multiple studies implicate this pathway in promoting tumour growth." (PMID 40899118, 2025). "The aim of this study was to determine the concentrations of IL-21 and IL-22 in a group of patients with invasive cancer, depending on the biological type of the tumour and its malignancy grade." (PMID 40729006, 2025). "In HCC, IL-22 is significantly upregulated in tumor-infiltrating leukocytes compared to peripheral lymphocytes, particularly in patients with advanced-grade tumors." (PMID 40806452, 2025). "At the same time, IL-22 can promote angiogenesis, which supports the migration and metastatic capacity of tumor cells." (PMID 40362280, 2025).
tumor (continued). "It was observed that tumors grew much faster and had larger tumor volumes in mice simultaneously treated with sorafenib and IL-22 than those in mice exposed to sorafenib alone." (PMID 38596684, 2024). "Theproduction of cytokines, including IL-17 and IL-22, by γδT cells plays a vital role in shaping the tumor microenvironment (TME), thereby influencing tumor growth in various contexts." (PMID 38576617, 2024). "Taken together, IL-22-regulated Il33 was specifically related to hepatocyte proliferation, whereas Steap4 was involved both in hepatocyte proliferation and tumor progression." (PMID 38533053, 2024). "IL-22 has previously been reported to promote liver regeneration, while facilitating tumor development in the liver via Steap4 upregulation." (PMID 38533053, 2024). "Others have suggested to therapeutically target (and thus inhibit) IL‐22, as there is evidence that it promotes tumor angiogenesis." (PMID 38363052, 2024). "IL-22 was the most frequently expressed cytokine (96.8% of patients) and showed strong staining in tumour and peritumour matrix tissues (strong expression [ST]: 82.3%)." (PMID 38643339, 2024). "It is thus possible that IL‐22 enhances intestinal, as well as other tissue, tumor growth and development by promoting angiogenesis." (PMID 38363052, 2024). "As a result, IL-22 is potentiated to activate the downstream JAK3-STAT3 pathway to achieve a greater expression of BTN2A1 on the NPC tumor cells." (PMID 39769218, 2024). "Of note, in vitro and in vivo studies conducted on SCC models showed that SOCS3 (and SOCS1) forced expression by SOCS3-derived peptide (KIR-ESS, see paragraph 4.1) efficiently suppresses IL-22-induced tumor growth." (PMID 38975347, 2024). "This latter work supports an earlier report from St Paul and coworkers showing that the CoA synthesis pathway is enriched in CD8+ Tc22 cells, and that fueling T these cells with vitamin B5 boosts their IL-22 production and anti-tumor potential." (PMID 39501296, 2024). "If this is the case, then the effect of BRRF1 with the downregulated IL-22RA2 will amplify tumor progression induced by IL-22." (PMID 39769218, 2024). "Lastly, it was shown that IL‐22 promotes tumor angiogenesis by enhancing endothelial cell proliferation, survival, and migration." (PMID 38363052, 2024). "The role of IL22 and, therefore, AhR-dependent T helper cell differentiation in cancer progression, is context dependent, with both pro-tumor and anti-tumor roles described." (PMID 38339226, 2024). "As an example of cell-mediated immunity, Th17 cells produced interleukin-22, which promoted the growth, migration, and invasion of tumor cells." (PMID 38244585, 2024). "In the B16-huCD19 tumor model, significantly more IL-18 and IL-23, as well as a trend towards more IL-22 and IFNγ was detected in serum of mice receiving combination treatment when compared to mice receiving CART alone." (PMID 38730243, 2024). "Research indicates that IL-22, the signature cytokine of Th22 cells, is involved in the occurrence and development of tumours." (PMID 38475858, 2024). "IL‐22BP is not only important in preventing IL‐22 signaling in tumor formation but also in continuous regulation of IL‐22 signaling in the intestine of healthy individuals where it helps to maintain homeostasis." (PMID 38363052, 2024). "In summary, this study demonstrated that IL-22 and PI3K/AKT signaling pathways play important regulatory roles in CRC development and revealed the mechanism of IL-22 in tumor cell invasion and metastasis." (PMID 39073546, 2024). "Recent studies revealed that IL-22 enhances immune cell infiltration in the tumour and increases malignancy." (PMID 38643339, 2024). "Compared to the sorafenib group, the sorafenib + IL-22 group had faster tumor growth and larger tumor volume, indicating the effect of IL-22 on sorafenib resistance in vivo." (PMID 38596684, 2024).
tumor (continued). "On another note, IL-22RA2 has a regulatory role, as it is constitutively expressed in various tissues, but in cancer, it appears to be decreased, which can allow IL-22-induced tumor growth." (PMID 39769218, 2024). "Gene therapy aimed at driving expression of IL-22BP, a secreted binding protein that inhibits IL-22 signaling, can alleviate tumor burden in mice." (PMID 38918278, 2024). "Interleukin-22 also induced tumor cells to express CD155, which inhibits the function of NK cells and supports tumor cell metastasis." (PMID 38244585, 2024). "In malignant tumors, increases in Treg cells can obstruct effective anti-tumor immune responses and IL-22 secreted by ILC3, contributing towards tumor growth." (PMID 38518996, 2024). "Th17 cells express the cytokines IL-17, IL-21, IL-22 and other cytokines such as IFNγ and TNFα in human tumor tissues." (PMID 38833034, 2024). "IL-22 is involved in the development of tumor diseases, the excess presence of IL-22 in the tumor microenvironment promotes tumor growth, inhibits apoptosis, and facilitates metastasis via STAT3 pathway activation." (PMID 38879568, 2024). "Given the role of Th17 and Th22 cells in promoting tumor development, IL-17A, IL-17F, and IL-22 are also promising targets in CRC." (PMID 38918278, 2024). "They reported that Candida albicans triggers the secretion of inflammatory IL-7 and leads to a metabolic shift to glycolysis through subcutaneous macrophages, ultimately inducing IL-22 secretion from innate lymphocytes and promoting tumor growth." (PMID 38835386, 2024). "On the other hand, Th17 cells inhibit tumor angiogenesis by secreting TNF-α, IFN-γ, IL-17F, IL-21 and IL-22, which inhibit tumor growth and promote the apoptosis of cancer cells." (PMID 39534095, 2024). "Th22 cells are significantly increased in PC tissues, and their production of IL-22 is able to promote tumor development." (PMID 37529035, 2023). "One subgroup of the cytokines is associated with tumour growth, inflammation, tumour progression and invasion (e.g. IL1, IL17, IL22), and another subgroup includes genes associated with antitumour response (e.g. IL2, IL5, IL12 and IFN family)." (PMID 36649303, 2023). "IFN-γ is an important product of ILC1s and has been identified as a critical cytokine in tumor immunosurveillance, whereas IL-22 is a potential tumor-promoting factor." (PMID 37122757, 2023). "As found in animal studies, the genetic silencing of IL-22 (IL-22 knockout mice) has led to a strong decrease in tumor size." (PMID 37894302, 2023). "Th17 cells have protumorigenic effects in various tumors, including PC; they mostly act in the early stage of the tumor, with IL-17 and IL-22 as effector molecules of Th17." (PMID 37529035, 2023). "In tumor tissue, it was observed that IL-22 and IL-22R1 were mostly expressed in tumor cells and to a lesser extent in stromal cells." (PMID 37835465, 2023). "According to the type of tumor, ILC3s produce cytokines including IL-17 and IL-22 that promote or inhibit tumor development." (PMID 37510993, 2023). "Although the increased ILC3-derived IL-17 and IL-22 production in the spleen observed in the tumor-free model was lost in the tumor challenge model, there was an opposite shift in NCR+ and NCR− ILC3 populations in the lungs." (PMID 36768726, 2023). "This is probably due to the effect of IL-22, which has been shown to inhibit apoptosis and promote tumor cell proliferation, angiogenesis, migration, epithelial-to-mesenchymal transition, and metastasis." (PMID 36980536, 2023). "In multiple experimental mouse models including CAC, IL-22 secreted by ILC3 has been shown to contribute to tumor development through downstream STAT3 phosphorylation and activation." (PMID 37122757, 2023). "Excessive IL-22 in the cancer microenvironment leads to tumor growth with the activation of the STAT3 pathway, and the epigenetic activation of genes with a STAT3-dependent pathway maintains the CRC stem cells." (PMID 37176567, 2023).
tumor (continued). "IL-1R1 ablation in T cells dampens the production of IL-17 and IL-22 that promotes tumor-elicited inflammation and tumor progression." (PMID 36932407, 2023). "In transplant patients, overexpression of IL-22 and IL-22R facilitate tumor growth and result in poorer prognosis." (PMID 36793738, 2023). "The study found secretion of IL-22 induced the expression of MUC1 on tumour cells allowing CAR-T cells to bind more accurately." (PMID 39935547, 2023). "For example, a study showed that IL-22 is an anti-tumor cytokine that inhibits tumor growth in mice." (PMID 37304260, 2023). "In KRAS-mutant lung cancer, inhibiting MEK increases the expression of TGF-β, IL-6, and IL-23, promoting the differentiation of Th17 cells and the secretion of IL-17 and IL-22, thereby enhancing tumor resistance, invasiveness, and metastasis." (PMID 37680632, 2023). "Another investigation revealed an increased IL-22 level in the higher stage of breast carcinoma, and its depletion limited tumor invasion and progression and decreased tumor burden." (PMID 37835465, 2023). "Higher T regs and lower CD8+ T cells, which result in decreased immune surveillance, and increased exposure to IL-22, which enhances tumor proliferation, represent two main factors that contribute to the aggressive nature of TSCC." (PMID 36793738, 2023). "Another study showed that IL-22 promotes CRC development in a Helicobacter hepaticus-induced tumor model." (PMID 37304260, 2023). "The increase in tumor-promoting gut bacteria in the mouse model of colorectal cancer induced by the APC gene upregulated IL-1R1 expression on T cells, which in turn stimulated the production of IL-17 and IL-22, thereby promoting tumor progression." (PMID 37680632, 2023). "Both Th17 and ILC-3 cells produce IL-17, which inhibits tumor cell proliferation, and IL-22, which promotes tumor growth and relapse, setting up a balance between growth promotion and inhibition modulated by environmental effects." (PMID 37296983, 2023). "The IL-1 (β in humans, α in mice) activated the NLRP3 Inflammasome in the tumor microenvironment and induced IL-22 production in various CD4+ T-cells including Th22, Th17, and Th1 cells." (PMID 37835465, 2023). "The presence of IL-17 increases tumor resistance by upregulating CD38, while IL-22 is associated with EMT, strengthening tumor invasiveness and metastasis." (PMID 37680632, 2023). "The role of IL-22 in cancer is complex since IL-22 was shown to either promote or restrain tumor progression." (PMID 37234993, 2023). "Another process linking dysbiosis to tumor cell proliferation is mediated by IL-22, whose production is activated in many infectious and inflammatory disorders." (PMID 37894302, 2023). "Overexpression of IL-22 and IL-22R accelerate tumor proliferation and subsequently result in poorer prognosis in transplant patients with cSCCs." (PMID 36793738, 2023). "Levels of the critical tumor-promoting TNF and IL-6 sera were low, but mucosal-healing IL-22 also supports tumor formation." (PMID 37275854, 2023). "Tc17 cells (characterised by IL-17A, IL-17F, IL-21, IL-22 production and low levels of granzyme B) have been associated with both anti-tumour (esophageal SCC patients) and pro-tumour activity (HNSCC patients)." (PMID 35406451, 2022). "This was demonstrated in models of breast and lung cancers in which neutralization of IL-1R signaling with anakinra abrogated IL-22 production and reduced tumor growth." (PMID 35517498, 2022). "With regard to the cytokine interleukin (IL)-22, dichotomous functions with partial tumor-promoting effects have been described in many studies." (PMID 36551508, 2022). "Taken together, IL-22 exerts its tumor-promoting effects mainly via IL-22RA1-mediated signaling on hepatocytes." (PMID 36551508, 2022). "In transgenic mice, treatment with anti-IL-22 antibodies together with subcutaneous injection of primary CRC cells strongly impaired tumor development and growth." (PMID 35884974, 2022).
tumor (continued). "IL-22 induces tumor-elicited inflammation from the T lymphocytes (CD4+ T cells) production via the activation of STAT3." (PMID 35563678, 2022). "In order to determine the effect of IL-22 on a series of signaling pathways involved in cell cycle control, cell proliferation, and tumor growth, the activity of p38-MAPK/AKT/JAK-STAT was detected in PC9 and A549 cells." (PMID 35669104, 2022). "It has also been suggested that IL-6, IL-22, and IL-10 can influence tumor drug resistance by regulating apoptosis-related proteins like BCL-2 and IAPs." (PMID 36245983, 2022). "While described as tissue-protective, the ILC3 signature cytokine, IL-22, was shown to promote carcinogenesis, which depended on the balance between tissue regeneration and tumor development in the intestine." (PMID 35300331, 2022). "On a functional level, in vivo studies in colitis-associated cancer were able to confirm that TGFβ relevantly contributed to the intratumoral accumulation of IL-17A+ IL-22+ CD4+ T cells and thereby obviously triggered IL-22-dependent tumor-promoting effects." (PMID 36428508, 2022). "A number of studies have shown that the tumor tissue in MF contains an increased amount of IL17 and IL22, and the rise in IL17 expression is associated with the disease progression." (PMID 35237320, 2022). "Many studies imply that IL-22 exerts its tumor-promoting effects directly by inducing a STAT3-mediated signal cascade in the malignantly transformed hepatocytes." (PMID 36551508, 2022). "The IL-10 family consists of six cytokines with IL-10, IL-19, IL-20, IL-22 and IL-26 described as tumor promoting." (PMID 36611932, 2022). "The absence of IL1R1 in T cells inhibits the production of IL‐17 and IL‐22, reducing the tumour‐induced inflammation, whereas in myeloid cells it increases the bacterial infiltration into the tumour tissue and triggers a pro‐tumorigenic inflammatory response." (PMID 36433652, 2022). "We further performed correlation analysis between IL22RA1 and tumor infiltrating immune cells in different types of cancer, as IL22 is produced mainly by immune cells." (PMID 35874683, 2022). "In the next step, we sought to investigate possible mechanisms and cellular targets, through which IL-22 promotes tumor development." (PMID 36551508, 2022). "IL22RA1 is an important heterodimeric receptor for interleukin 22 (IL22) which is involved in chronic inflammation and tumor development." (PMID 35874683, 2022). "Here, we identified hepatocytes as the main cellular target of IL-22 during liver carcinogenesis in vivo and showed that signaling of this cytokine on endothelial cells is dispensable for overall tumor development." (PMID 36551508, 2022). "IL-22 promotes tumor angiogenesis by stimulating endothelial cell proliferation, survival, and migration." (PMID 35626056, 2022). "Recent scientific evidence suggests that the promoting effect of IL-22 on CRC development occurs via the induction of stemness in tumor cells." (PMID 36466926, 2022). "In contrast, in breast cancer, IL-22 produced by hILC3s impelled tumor proliferation and metastasis." (PMID 36246629, 2022). "In contrast, IL-5, IL-17A, IL-21, IL-22, and TGFβ concentrations in the tumour tissue of IL-9 knockout mice were significantly reduced compared with wild-type mice, indicating that IL-9 controls the production of Th2- and Th17-associated cytokines." (PMID 35793807, 2022). "Its activity drives intestinal inflammation by inducing other proinflammatory cytokines, such as IL-6, IL-17, and IL-22, and therefore promotes tumor cell survival." (PMID 35884974, 2022). "Using MR-imaging, we likewise found a reduction in tumor volume in IL22-/--mice, while IL22bp-/--mice displayed an increased tumor volume." (PMID 36551508, 2022).